KIF11 (kinesin family member 11)
Diseases named in the same sentence as KIF11 in open-access papers (continued):
Sharing a sentence is not in itself a finding about the gene and the disease.
tumor (continued). "Our data showed that 4bt, one of the KIF11 inhibitors evaluated on this work, was able to hold tumor growth when used as monotherapy, however it presented more pronounced antitumor effects when used in combination with other drugs, as already pointed for other KIF11 inhibitors." (PMID 34548908, 2021). "KIF11 depletion inhibits cell proliferation and tumor growth in vitro and in vivo." (PMID 33490265, 2021). "Treatment with KIF11 inhibitor decreases intratumoral necrotic area To assess antiproliferative and antitumor effects of the treatments proposed on this work, histopathologic analysis of tumor sections of all animal groups were performed after HE staining." (PMID 34548908, 2021). "Only 7.35% of the cases had KIF11 overexpression, whereby this expression pattern included patients whose tumors simultaneously exhibited high KIF11 staining intensity (mostly strong 3+ staining) on at least 25–49% of tumor cells." (PMID 34208606, 2021). "Aberrant upregulation of kinesin family members could lead to uncontrolled tumor growth, and hence mitotic kinesin inhibitors such as KIF11-targeted inhibitors and CENPE-targeted inhibitors have attracted great attention in drug development." (PMID 33995648, 2021). "We also performed mRNA-level analysis of KIF11 in 10 paired tumor-normal samples in GSE139682." (PMID 33613109, 2021). "Ispinesib, a KIF11-inhibitor, effectively inhibited tumor proliferation in all seven cell lines." (PMID 34079014, 2021). "Furthermore, this inhibitor has shown other interesting roles for tumor inhibition, like down-regulation of KIF11 and ALDH1-A1, particularly when combined with existing treatments." (PMID 34548908, 2021). "KIF11 increasingly expressed in high stage and malignant tumor cells." (PMID 32346924, 2020). "We hypothesized that targeting Kif11 or Aurka to block the Id1-Kif11/Aurka axis may cause the Id-expressing CSC to be more vulnerable to chemotherapy and more effectively debulk the entire tumor mass." (PMID 32911668, 2020). "As expected, KIF11 inhibitor significantly reduced the tumor volume." (PMID 29190901, 2017). "Altogether, these data indicated that KIF11 could be a therapeutic target in treating resistant TNBC, as KIF11 inhibitor significantly inhibits the tumor growth in vivo." (PMID 29190901, 2017). "It was apparent that tumor growth was effectively controlled by KIF11 inhibitor SB743921." (PMID 29190901, 2017). "Overexpression of KIF11 has been shown to promote tumour development of multiple cancers." (PMID 27128470, 2016). "In our analysis, KIF11 expression correlated positively with immune cell infiltration, raising the possibility that KIF11 may also facilitate immune cell mitosis and thereby contribute to anti‐tumor immunity." (PMID 41189590, 2025). "In addition, the function of KIF11 in the lymphatic system suggests the possibility that KIF11 may indirectly affect tumor progression via immune functions." (PMID 38464517, 2024). "Although predictions made from these experiments are consistent with in vivo studies of combinations of ispinesib and saracatinib in murine GBM models, it remains possible that local variations in microenvironment from tumor to tumor may alter the efficacy of combined Kif11 and STAT3 targeting." (PMID 35732128, 2022). "KIF11 may play multifaceted roles in tumor by influencing the infiltration of neutrophil." (PMID 36742345, 2022). "KIF11 expression had significant associations with heterogeneity related factors, such as homologous recombination deficiency (HRD), loss of heterozygosity (LOH), tumor mutational burden (TMB), microsatellite instability (MSI), mutant allele tumor heterogeneity (MATH), and ploidy." (PMID 36742345, 2022). "Furthermore, the function of KIF11 in lymph system implied the possibility that KIF11 might influence tumor progression through immunity indirectly." (PMID 36742345, 2022).
tumor (continued). "In addition, we also conducted the sphere formation assay, where KIF11‐driven tumor stemness features could be notably suppressed with SREBP2 knockdown." (PMID 35619540, 2022). "However, it fits well with the functional portrait of KIF11 in most tumor types studied to date." (PMID 34575892, 2021). "Furthermore, KIF11 knockdown significantly reduced tumor size and weight, which might be due to downregulation of N-cadherin and vimentin as well as reductions in ERK, AMPK, AKT, and CREB phosphorylation." (PMID 33968780, 2021). "Furthermore, KIF11 expression was significantly correlated with tumor stage of LUAD." (PMID 33968780, 2021). "Furthermore, Gene sets Enrichment Analysis suggests that KIF11-mediated tumor cell proliferation might through the activation of PI3K/AKT signaling pathways." (PMID 33613109, 2021). "Moreover, our results from human tumor xenografts in nude mice indicated that inhibition of KIF11 could reduce tumor growth in vivo." (PMID 33613109, 2021). "The prognostic performance of KIF11 and miR‐30a could be compared with age, tumor size, and grade." (PMID 32346924, 2020). "Among these, seven genes, namely, RRM2, KIF11, ANLN, CDC20, YWHAZ, DTL, and PCNA, exhibited significantly elevated expression in tumor samples (p ≤ 0.05)." (PMID 41487287, 2025). "Knockdown of KIF11 leads to G2/M phase arrest, indicating its crucial role in TNBC tumor cell proliferation and self-renewal, both in vitro and in vivo." (PMID 40092695, 2025). "In summary, these studies collectively establish a clear link between tumor progression and three kinesin genes (KIF4A, KIF20A, and KIF11)." (PMID 41462522, 2025). "Among the MUGs, high expression of KIF11 and RCC1 was commonly correlated with high tumor grades (G2 and G3) and unfavorable clinical outcomes (treatment response-PD, SD, and post-treatment outcome-RP)." (PMID 38741142, 2024). "KIF11, KIF23, and KIF14 are motor proteins involved in mitosis and intracellular transport that can influence tumor growth and spread, possibly affecting recruitment and localization of immune cells within TME." (PMID 39083127, 2024). "IHC score indicated that PRR11, KIF11, RACGAP1, YY1, CREB1 expression was significantly increased in HCC tissues compared to adjacent para-tumor tissues." (PMID 39530087, 2024). "We identified a combination of mitotic inhibitors targeting KIF11 (SB-743921) and AURKA that are effective in inhibiting EWS tumor growth at physiologically relevant nanomolar doses." (PMID 37894278, 2023). "In this study, we employed a synergistic combination of mitotic inhibitors targeting KIF11 and AURKA to halt EWS tumor growth in vitro and in vivo, as assessed in a mouse xenograft model." (PMID 37894278, 2023). "Last, we further constructed the subcutaneous xenograft models and found that atorvastatin was proved to be effective to suppress KIF11‐OE PDAC progression, as quantified by tumor volumes and tumor weights." (PMID 35619540, 2022). "KIF11 was primarily involved in cell cycle, TME alteration and tumor-infiltrating immune cells proportions." (PMID 35515103, 2022). "The expression of KIF11 was diverse in different immune subtypes and remarkably correlated with ESTIMATE, immune checkpoint, and immune cell infiltration in the tumor microenvironment." (PMID 36742345, 2022). "Moreover, KIF11 could be a novel target for tumor immunotherapy." (PMID 36742345, 2022). "When analyzed as continuous variables, a significant increase in staining intensity was found for KIF11 and KIF14 in tumor tissue compared to normal adjacent tissue (both p < 0.0001, Mann–Whitney test)." (PMID 34208606, 2021). "Specifically, a mechanistic explanation for the clinical significance of the predominant expression pattern of KIF11 in PDAC, i.e., moderate intensity (median IS = 2) on a low percentage of tumor cells (median PS = 1), remains elusive." (PMID 34208606, 2021).
tumor (continued). "The expression of KIF11 was negatively correlated with the overall survival (OS) and disease-free survival (DFS) and positively correlated with tumor size of HCC patients." (PMID 33490265, 2021). "Nevertheless, although not reaching significance, there was a trend of reduced expression of PLK1, KIF11, PTTG1 and TTK (the latter otherwise induced by DEXA in U25MG cells in DEXA treated tumours." (PMID 33478100, 2021). "KIF11 and KIF14 staining was localized to the cytoplasm and to the cytoplasm and/or membrane of tumor cells, respectively." (PMID 34208606, 2021). "In our analysis, we found that KIF11 was among the most frequently dysregulated kinesins in CRC, and its knockdown markedly impaired cell proliferation in vitro and tumor growth in vivo." (PMID 33995648, 2021). "The gene target of ispinesib, KIF11, co-localized with mitotic figures in both ATRT and MB, which makes this drug a good target against actively dividing tumor cells." (PMID 34079014, 2021). "In turn, mRNA levels of KIF11 and KIF14 were markedly elevated in tumor tissues compared to normal tissues, and this coincided with adverse prognosis, even after adjusting for multiple confounders." (PMID 34208606, 2021). "The top five lethal siRNAs in VU-preSCC-M3 were directed against KIF11, RRM1, NHP2L1, WEE1 and SF3B1, and all showed effect in at least 9 of 12 tumor cell lines." (PMID 32047167, 2020). "In tumor tissues, CCNB2, DYNC1LI1, SPC25 and KIF18A expressions were mainly detected in the cytoplasm, and KIF11 expression was detected mainly in the cytoplasm and nucleus." (PMID 33111935, 2020). "In line with previous findings, we identified KIF11 as an oncogene during tumorigenesis of HBV-HCC, and its expression level was significantly higher in tumor samples compared with adjacent normal tissues." (PMID 33376723, 2020). "In conclusion, in this study, we present extensive evidence to demonstrate that KIF11 is critical for proliferation and self-renewal in TNBC tumor cells, in vitro and in vivo." (PMID 29190901, 2017). "qPCR analysis were performed for the genes KIF11, ASPM and MT3 in the tumours previously analyzed by gene-expression microarray." (PMID 20885975, 2010). "Unlike KIF11, the expression of KIF14 did not exhibit a significant association with tumor grade in our study." (PMID 40075652, 2025). "Of these hub genes, only four genes, CDK1, NDC80, KIF11, and COL4A2, were shared between the two groups, whereas 189 hub genes from the normal group replaced 101 different hub genes from the tumor group, resulting in protein–protein network differences between the normal and tumor groups." (PMID 40457491, 2025). "Additionally, in glioblastoma tumor-initiating cells that perform angiogenesis and invasion, APC/CCDH1 has been confirmed to be defective, leading to the stabilization of KIF11 throughout the cell cycle." (PMID 38672404, 2024). "Following that, the top 100 correlated proteins with CEP55 were collected from the GEPIA2 database, where the proteins KIF11, MK167, CDK1, PLK1, and CCNA2 represented the top 5 proteins correlated with CEP55 in the tumor microenvironment that influence immune cells in TME." (PMID 37175004, 2023). "Next we examined subcompartment repositioning involving the tumour suppressors XRCC5 and KIF11." (PMID 36922594, 2023). "Besides, KIF11 depended on elevated SREBP2 proteins to drive MVA crosstalk, and targeting the MVA pathway is effective to suppress tumor growth." (PMID 35619540, 2022). "Indeed, the present study showed that CCNA2, CEP55, KIF11, KIF4A, and ZWINT were the top five genes that were significantly and positively correlated with CDK1 in all tumor types from the TCGA database." (PMID 35681641, 2022). "Additionally, KIF11 was primarily involved in cell cycle, TME alteration and tumor-infiltrating immune cells proportions." (PMID 33968780, 2021).
tumor (continued). "The total expression scores for KIF11 tended to be decreased in tumor tissues relative to adjacent non-tumor tissues (p = 0.09, Mann–Whitney test), whereas for KIF14, a statistically significant increase was found (p < 0.0001, Mann–Whitney test)." (PMID 34208606, 2021). "In addition, we also uncovered a strong correlation between KIF11 expression and clinical pathological parameters, such as OS, DFS, tumor size, and malignancy of HCC." (PMID 33490265, 2021). "We found that KIF11 is overexpressed in HCC tissues, and KIF11 shRNA significantly inhibits proliferation and tumor formation of HCC cells, suggesting that KIF11 may serve as an effective target for the treatment of HCC." (PMID 33490265, 2021). "KIF11 was again expressed on different cell populations within PDOX tumor, and not restricted to mitoses, indicating ispinesib targeted not only mitoses (actively dividing cells) but also other tumor cell populations within the tumor." (PMID 34079014, 2021). "Kinesin family member 11 (KIF11), a kinesin-5-family protein, could affect tumor development by controlling the correct arrangement of the microtubules, which was the key stage in mitosis." (PMID 32411535, 2020). "All these data indicate that KIF11 is critical for proliferation and self-renewal in TNBC tumor cells in vitro and in vivo, suggesting that KIF11 may be a promising therapeutic target for treating chemoresistant TNBC." (PMID 29190901, 2017). "Since KIF11/Eg5 and KIF20A/Mklp2 are promising drug targets, we sought to investigate the impact of their respective inhibitors on angiogenesis, a process that is central to tumor progression." (PMID 24327603, 2013). "In the light of our in vitro results on Eg5/KIF11 inhibition of endothelial cells, it can be expected that Eg5 inhibition might have a dual effect as it affects both malignant cells and tumor vasculature." (PMID 24327603, 2013). "While this trend was not statistically significant, it may indicate that KIF11 plays a role in tumor progression and dedifferentiation." (PMID 40075652, 2025). "Additionally, agents targeting KIF11, such as SRI36666, have been identified and may serve as potential therapeutic options for inhibiting tumor progression in CRC." (PMID 40457491, 2025). "In addition, 113 hub genes from the normal group, 48 hub genes from the tumor group, and 2 hub genes (CDK1 and KIF11) from both groups were included in the 9427 DEG (p ≤ 0.001 and p ≤ padj) sets, indicating differential expression between the normal and tumor tissues." (PMID 40457491, 2025). "Pudova and colleagues found a strong negative correlation between KIF11 expression and tumor progression-free survival, thus confirming the fact that an Eg5 expression leads to worse PC prognosis for patients compared to those with lower levels of Eg5." (PMID 38939361, 2024). "However, BUB1, CCNB1, BUB1B, KIF11, CDC20, TTK, and NCAPG, which are closely related to regulation of the cell cycle and DNA repair, showed strong positive correlations with tumor purity in luminal-type BC." (PMID 34733851, 2021). "Similarly, knockdown KIF11 inhibited the proliferation of HCC cells and tumor growth in vivo." (PMID 33490265, 2021). "Although the role of KIF11 in tumor growth of CRC has not been thoroughly investigated 19, the evidence showing that it is required for mitosis and cell proliferation hints that it might possess a pivotal function in CRC." (PMID 33995648, 2021). "KIF11 (target of ispinesib) was expressed on different cell populations within PDOX tumor and patient tumor, and not restricted to mitoses, indicating ispinesib targeted not only mitoses (actively dividing cells) but also other tumor cell populations within the tumor." (PMID 34079014, 2021). "We found that KIF11, ERBB2, PI3K, AKT and phosphorylated AKT protein were downregulated after KIF11 siRNA transfection, whereas transfection of ERBB2 plasmids could partially restore this reduction in KIF11 knockdown tumor cells." (PMID 33613109, 2021).
tumor (continued). "Multivariate Cox proportional hazards models validated high KIF11 (adjusted HR = 0.32, 95% CI 0.11–0.89; p = 0.03) and KIF11+KIF14 (adjusted HR = 0.22, 95% CI 0.07–0.71; p = 0.01) as positive, and advanced tumor stage as negative, markers for OS." (PMID 34575892, 2021). "Many of the key regulators in the canonical oncogenic (tan) module were involved in the processes leading to tumor cell proliferation and survival (TPX2, NCAPH, KIF11, NUSAP1, KIF23, MCM10) but most of them have not been associated with pediatric tumors." (PMID 31988326, 2020). "And the KIF11 expression comparison between TNBC and non-TNBC demonstrates that high level of KIF11 expression tends to be a more aggressive tumor subtype." (PMID 29190901, 2017). "Thus, for a KIF11 inhibitor to be therapeutically active in GBM, it needs not only to cross the BBB, but be retained within both brain and tumor at effective concentrations for considerable periods of time in order to target a substantial proportion of tumor cells when they are vulnerable." (PMID 32300151, 2020).